MUC1 (mucin 1, cell surface associated)
Diseases named in the same sentence as MUC1 in open-access papers (continued):
Sharing a sentence is not in itself a finding about the gene and the disease.
tumor (continued). "In the present report, we retrospectively investigated immunohistochemical expression and subcellular localization of MUC1 in primary tumors and examined their relationship to tumor malignancy, chemotherapy effect and patient outcomes." (PMID 37002293, 2023). "Across these samples, MUC16 expression was merely limited to two epithelial tumor cell clusters, whereas expression of other mucins (like MUC1) was more uniformly distributed across the epithelial and SMC/myoepithelial cell clusters." (PMID 36816942, 2023). "Second-generation MUC1-CAR-T cells exhibited relatively high tumor antigen specificity, strong tumor cytolytic activity, and elevated cytokine production." (PMID 37457288, 2023). "MUC1 is commonly overexpressed and reveals specifically altered glycosylation in tumor cells in comparison with normal cells." (PMID 37685842, 2023). "Of note, MUC1 has been the focus of chimeric antigen receptor T cell (CAR-T) as well as antibody-drug conjugate development efforts for other tumor types." (PMID 36821396, 2023). "CA15-3, one of the mucin glycoproteins (MUC1), is widely used as a tumor marker for the diagnosis of BC." (PMID 36619680, 2023). "To further explore the relationship between MUC1 and immune cells in the TME, we examined metastasis-associated immune cells in paired primary tumor and lung metastasis tissues from the same patient using Fluorescent Multiplex Immunohistochemistry." (PMID 36738352, 2023). "Another study demonstrated that CAR T-cells engineered to recognise the tumour-specific Tn glycoform of MUC1 neoantigen controlled tumour growth and prolonged survival." (PMID 37686543, 2023). "With the deepening of anti-tumor immune mechanisms, MUC1-based vaccines have become a major concern in the clinical diagnosis and treatment of cancer." (PMID 37894512, 2023). "Examples of TAAs are carcinoembryonic antigen (CEA), the transmembrane glycoprotein Mucin 1 (MUC1), and melanoma-associated antigen (MAGE), each of which ranges from overexpression to aberrant expression in specific tumor types." (PMID 38203656, 2023). "The resistance of paclitaxel (PTX) to NSCLC is related to the expression of MUC1 on the surface of tumor cells." (PMID 36778203, 2023). "In tumor cells, the transmembrane glycoprotein MUC1 is post-translationally modified, resulting in incomplete O-glycosylation and exposure of the TF epitope." (PMID 37898403, 2023). "MUC-1 expression has been found to increase when primary BC acquires a more aggressive phenotype, and its high expression is correlated with higher tumor grade and worse prognosis." (PMID 37110670, 2023). "The tumor multiplicity in MUC1.Tg mice vaccinated with MUC1 + BMDCs was significantly lower compared to mice vaccinated with BMDCs (p < 0.05) and mice vaccinated with pcDNA + BMDCs (p < 0.05)." (PMID 36980805, 2023). "In comparison, three studies commented on the use of MUC1 gene expression in the primary tumour as a predictor of cancer metastasis, and one study on the presence of MUC1 as a predictor of lymph node (LN) recurrence." (PMID 37958425, 2023). "These included Role of Altered glycosylation of MUC1 in the tumour microenvironment, Nod-like receptor (NLR) family proteins and cytosolic DNA sensing." (PMID 36442992, 2023). "Instead, peptide vaccines and dendritic cell vaccines have targeted other tumor-associated antigens (TAAs), including WT1, PR3, RHAMM, and MUC1." (PMID 37513844, 2023). "Several studies have shown that MUC1 plays a key regulatory role in tumor invasion, metastasis, angiogenesis, and inflammation." (PMID 38115130, 2023). "In contrast, vaccination with MUC1 DNA alone or BMDCs alone was ineffective in reducing tumor burden." (PMID 36980805, 2023). "Two murine MUC1-derived epitopes were used to generate VELs, which reduced tumor area and lung metastasis." (PMID 37243023, 2023). "Of note, CEA- and MUC1-specific T-cell responses were observed in most patients as cascade Ags, suggesting potential tumor cell disruption." (PMID 36679991, 2023).
tumor (continued). "The cytotoxic effect of activated T cells was also evaluated using co-cultivation of tumor organoids and engineered T cells targeting MUC1, an antigen highly expressed in both primary tumors and their derived organoids." (PMID 35565191, 2022). "Chitosan is shown to possess mucoadhesive properties, as it shows an affinity for the MUC1 adhesion molecule (CD227), a cell membrane glycoprotein, overexpressed by tumor cells." (PMID 36531004, 2022). "MUC1 is an abnormally glycosylated extracellular transmembrane glycoprotein that is correlated with poor survival and tumor progression." (PMID 35720364, 2022). "The peptides from the VNTR sequence are often used as the antigens for tumor vaccines targeting MUC1." (PMID 36499455, 2022). "Despite extremely high tumor heterogeneity, malignant cell markers such as MUC1, CEACAM5, S100A11, CD24, and TM4SF1 were relatively uniformly upregulated in cancer cells and had the potential to serve as targets for SBA diagnosis and treatment." (PMID 36104333, 2022). "Then, we demonstrated that SZU251 + MUC1 + Al was effective and safe against a tumor expressing the MUC1 antigen in both prophylactic and therapeutic schedules in vivo." (PMID 36499455, 2022). "Knockout of either MUC1 or MUC13 retarded tumour growth, but the knockout of both achieved the greatest tumour regression." (PMID 35292781, 2022). "Next, for translation to adrenal-related applications, the human adrenocortical cell lines NCI-H295R and MUC-1 were seeded to Sphericalplates and investigated for successful tumor spheroid formation as well as ongoing spheroid growth." (PMID 35879289, 2022). "Peptides used to develop vaccines are derived from tumor-associated antigens or tumor-specific antigens, such as HER-2, MUC1, ErbB2, CEA, FRα, MAGE A1, A3, and A10, NY-ESO-1, among others." (PMID 36016136, 2022). "There remains an unmet need and an importance in developing novel MUC1 vaccine approaches to activate the immune system and overcoming the immunosuppressive tumour microenvironment." (PMID 36307410, 2022). "A fourth pathway is MUC1’s suppression of tumor cell proliferation and apoptosis, which is related to regulating diverse tumor cell proliferation/apoptosis pathways." (PMID 35883508, 2022). "Herein, we evaluated the preclinical efficacy of a recombinant nanobody against MUC1 tandem repeats in suppressing tumor growth, angiogenesis, invasion, and metastasis." (PMID 34694686, 2022). "To enhance NK cell tumor specificity, we generated a MUC1.BiKE to provide antigen engagement to these NK cells, and confirmed that the MUC1.BiKE increased NK cell killing of SUM-159 cells to 69% lysis compared to 43% at baseline." (PMID 35681750, 2022). "Compared to their unspecific control sequences, a 43-fold and 32-fold higher tumor accumulation of AS1411 and MUC1 targeted nanoprobes was measured in MCF-7 tumor xenografts 6 h post intravenous injection." (PMID 35673581, 2022). "A significant decline in expression of Ki‐67 marker in treatment group also proposes the tumor suppressive activity of anti‐MUC1 therapy." (PMID 34694686, 2022). "A tumor vaccine has been constructed by covalent attachment of an MUC1 glycopeptide and a T-helper epitope, inducing both humoral and cellular immune responses." (PMID 36499455, 2022). "Tetanus toxin and sialyl-Tn epitope of MUC-1 were injected into mice bearing BC and decreased tumor growth in them." (PMID 35000604, 2022). "Gatipotuzumab, also known as PankoMab-GEX, is a humanized IgG1 anti-MUC1 mAb that binds with high affinity to a novel carbohydrate-induced conformational epitope on MUC1 (named tumour-related MUC1 epitope, TA-MUC1)." (PMID 35892707, 2022). "This study involves recombinant VLPs presenting multiple copies of tumour-specific mucin 1 (MUC1) epitope as a potentially powerful tool for future immunotherapy." (PMID 35351156, 2022).
tumor (continued). "For instance, Mucin-1 (MUC1) expression on tumour cells differ from normal cells, mainly due to an upregulation of gene expression and to O-glycans being truncated, mostly exhibiting core 1 O-glycan structures." (PMID 35454762, 2022). "Other than that, MUC1 expression promotes tumor blood vessel formation and partially enhances tumor invasion and metastasis." (PMID 35883508, 2022). "Taken together, the results indicate that overexpression of MUC1 plays a significant role in switching the TGF-β function from a tumor-suppressor to a tumor promoter by directly activating JNK." (PMID 35237602, 2022). "Our study demonstrated that the MUC1 mRNA expression was remarkably lower in LUSC as opposed to that in normal lung specimens, and differential MUC1 expression was observed during the tumour stage progressing from I to IV." (PMID 36059804, 2022). "miR-145 also functions as a tumor suppressor by directly targeting the 3′ UTR of MUC1 to suppress its protein expression; however, it acts in a cell-specific manner." (PMID 35154471, 2022). "MUC1 silencing reduces NF-κB activity in cancer cells; it further interrupts the self-renewal of tumor cells." (PMID 35248049, 2022). "Subunit vaccines contain tumor-related human MUC1 glycopeptides inducing potent anticancer humoral immunity in mice." (PMID 35883508, 2022). "As another mouse anti-MUC1 IgG1, AR20.5 (BrevaRex) is produced based on MUC1’s tumor-associated antigen in the backbone of the TP protein." (PMID 35883508, 2022). "The results showed significant differences in MUC1 between primary tumours and paraneoplastic tissues (p value < 0.002)." (PMID 35879749, 2022). "A transmembrane cleavage product of MUC-1, known as MUC-1*, which is the predominant form of this glycoprotein on cancer cells, functions as a growth factor receptor on tumor cells." (PMID 35000604, 2022). "In another study, DC vaccine fused with MUC1-mRNA in combination with anti-CTLA4 mAb -9D9- has increased anti-tumor immunity in TNBC mice models." (PMID 35248049, 2022). "It has been reported that glycosylation-modified MUC1 promotes tumor growth by regulating the epidermal growth factor receptor (EGFR) pathway in EC cells." (PMID 35752750, 2022). "The overexpression of HER2 in many malignant epithelial cells makes biCAR-T cells expressing HER2 and MUC1 efficient in tumor killing, inducing T cell proliferation, and eradicating antigen escape when encountering target cells." (PMID 35326556, 2022). "Some well-known secreted tumor markers include AFP, cell surface-associated protein (MUC1 or CA15-3), gastrin-releasing peptide, and prostate-specific antigen (or KLK3)." (PMID 35719915, 2022). "Alteration in glycosylation pattern of MUC1 mucin tandem repeats during carcinomas has been shown to negatively affect adhesive properties of malignant cells and enhance tumor invasiveness and metastasis." (PMID 34694686, 2022). "The authors studied the preclinical efficacy of a recombinant nanobody against MUC1 tandem repeats in suppressing tumor growth, angiogenesis, invasion, and metastasis." (PMID 34694686, 2022). "The expression of genes encoding mucins (MUC1, MUC2 and MUC5A) or involved in mucosa protection (TFF1 and TFF3) were positively correlated with AGR2 expression in most tumour types." (PMID 35857928, 2022). "In normal cells, MUC1 glycoproteins are expressed in a polarized fashion, whereas MUC1 glycoproteins in tumor cells are overexpressed with much less glycosylation, present all over the cell surface, and show an unpolarized fashion." (PMID 35371101, 2022). "MUC1 and FAS displayed the most stable expression levels between the tumor and normal tissue, even though the expression level of MUC1 was higher than that of FAS." (PMID 35054482, 2022). "In the FUSCC cohort, MUC1 absence was associated with increased proportion of stage III PDAC (p = 0.011), and MUC1 absence and MUC2 presence were associated with tumour perineural aggression (p = 0.011 and p = 0.030, respectively)." (PMID 35910854, 2022).
tumor (continued). "And comparing the PDL1-DCs and PBS-DCs groups, the MUC1-Vax DCs group of both tumor-bearing mice significantly improved the survival rate and prolonged the survival period of the tumor-bearing mice." (PMID 35891256, 2022). "Delay in tumor growth was evaluated over a 24‐day period following administration of anti‐MUC1 nanobody with concentration equal to 3 μg·g−1 in comparison with PBS receiving group." (PMID 34694686, 2022). "Treating Ishikawa cells with BenzylN-acetyl-·-galactosaminide and tunicamycin induced an increase in the adhesion ability of the cells, and reduced the binding of alpha2beta1 integrin and MUC1, inhibiting tumor growth and migration." (PMID 35752750, 2022). "Accordingly, thermo-sensitive cross-linked chitosan hydrogel as a double package nanodelivery system was adopted for local, sustained, and timely burst release of niosomes upon targeting MUC1 mucin surface antigen overexpressing tumor cells." (PMID 36531004, 2022). "Recently, it was found that humanized mAb 5E5 antibodies (CIM301-1 and CIM301-8) are potent enhancers of NK cell activation and cytotoxicity in vitro in MUC1-Tn/STn-positive tumor cells." (PMID 35158915, 2022). "A previous study proved that Muc1 acts as a tumor-related factor and is abnormally expressed in patients with IBD." (PMID 36479296, 2022). "Our results demonstrated that SZU251 + MUC1 + Al was effective and safe against a tumor expressing the MUC1 antigen in both prophylactic and therapeutic schedules." (PMID 36499455, 2022). "Muc1 has been targeted for tumor labeling using antibody-conjugated fluorophores and targeting peptides to image mouse model of pancreatic cancers." (PMID 35053365, 2022). "In line with the previous report, 4T1-MUC1 tumors also showed a resistance to PD-1 antibody or MUC1 vaccine alone treatment both in the tumor volumes and the overall survival of the treated mice." (PMID 35712073, 2022). "It was also found that MUC1-MBP-CPG ODN1826 significantly prolonged the survival of tumor-bearing mice in in vivo experiments." (PMID 35251013, 2022). "Then, we performed IHC to verify the differential expression of MUC1 between tumor tissues and adjacent normal tissues at the protein level." (PMID 36104333, 2022). "Premalignant lesions express several tumor antigens, including MUC1, Carcinoembryonic Antigen (CEA), and Human Epidermal Growth Factor Receptor 2 (HER2)." (PMID 36298592, 2022). "Consistent with activation of the type I IFN pathway, we found that MUC1 significantly associates with (i) STAT2 and IRF9 expression in TNBC tumors and (ii) IRF9 in a scRNA-seq dataset from TNBC tumor cells." (PMID 35681561, 2022). "These mAb recognize different amino acid sequences of aberrantly O-glycosylated MUC1, also known as the Tn antigen, expressed in a variety of tumor cell types." (PMID 35740244, 2022). "Among these genes, MUC1 is a marker protein characterized by the polarity reversal of IMPC tumor cell clusters." (PMID 35013309, 2022). "Targets such as CEA, EGFR, EpCAM, MUC1, and VEGF were also highlighted as promising tumor-associated targets by the National Cancer Institute." (PMID 35053365, 2022). "Chimeric VLPs presenting the anti-tumour antigens were described for antigens such as: MUC1, survivin, HER-2, carcinoembryonic antigen (CEA), Prostate Specific Antigen (PSA) and more." (PMID 35351156, 2022). "It has a strong reaction with the MUC1 cell surface epitope or its soluble form in diverse tumor cell types." (PMID 35883508, 2022). "Targeting MUC1-C in an immunocompetent TNBC GEMM in which mouse Eo771/MUC1 cells are engrafted onto human MUC1.Tg mice suppresses PD-L1 expression in association with increases in CD8+ T cells and tumor-cell killing." (PMID 35897789, 2022). "All of them also contained the complementary sequence to the MUC1 aptamer for binding to the surface of tumor cells." (PMID 36499129, 2022).
tumor (continued). "Concentration of pro‐inflammatory and pro‐angiogenic cytokines including IL‐1a, IL‐2, IL‐6, IL‐10, IL‐12, and IL‐17A, in peripheral blood of tumor bearing mice receiving anti‐MUC1 nanobody was significantly lower compared to the PBS receiving group." (PMID 34694686, 2022). "The expression of MUC1, CD44, and HA has been notably implicated in tumor cell migration and metastasis via several signaling pathways." (PMID 36359337, 2022). "This mAb is, therefore, displaying numerous advantages compared to other anti-MUC1 antibodies in clinical development with higher tumour specificity, higher affinity and rapid internalisation." (PMID 35892707, 2022). "It has been reported that MUC1 protein is expressed at high levels over the entire surface of tumor cells from diverse types." (PMID 36572921, 2022). "MUC1 expression was evaluated by immunohistochemistry on normal and pathological tissues, stratifying samples according to staining intensity as tumor with high MUC1 expression (MUC1H) and tumor with low MUC1 expression (MUC1L)." (PMID 36430448, 2022). "In the present study, we constructed a novel tumor vaccine (SZU251 + MUC1 + Al) containing MUC1 and two types of adjuvants: a TLR7 agonist (SZU251) and an aluminum adjuvant (Al)." (PMID 36499455, 2022). "In this report VLPs based on the structural protein of Norovirus (NoV VP1) were genetically modified to present multiple copies of tumour-specific MUC1 epitope on their surface." (PMID 35351156, 2022). "One limitation of the proposed immunotoxins would be their binding to soluble MUC1 fragments in serum, neutralizing their anti-tumor activity." (PMID 35740244, 2022). "MUC1 is a type I transmembrane protein that plays an important role in tumor cell signal transduction." (PMID 35879749, 2022). "According to ongoing researches, the significant correlation between enhanced expression of MUC1 in tumor cells, as well as amplification of cancer cell proliferation and metastasis, is related to modulation of multiple signaling pathways." (PMID 35248049, 2022). "In combination, MUC1 mRNA nanovaccine plus anti-CTLA-4 mAb appeared more effective than either nanovaccine or anti-CTLA-4 mAb alone at increasing level of apoptosis in tumor cells." (PMID 34875483, 2022). "MUC1 is a very promising tumor target, and the immune checkpoint PD-L1 also has great potential for tumor treatment." (PMID 35891256, 2022). "Altered expression of MUC1 glycosyltransferase results in a Thomsen–Friedenreich (TF) structure, which reduces the adhesion between tumor cells." (PMID 35784721, 2022). "Mucin1 (MUC1), a transmembrane glycoprotein highly overexpressed and aberrantly glycosylated on many tumor tissues including ovarian, breast, pancreatic, prostate and ovarian carcinomas." (PMID 35186882, 2022). "Mucin-1 (MUC1) is a Type I transmembrane glycoprotein that influences tumor progression and metastasis in PDA." (PMID 35237602, 2022). "Coculture of the AML cell lines or primary AML cells with donor PB mononuclear cells expanded M-MDSCs and prevented monocyte differentiation, probably by MUC1-mediated tumor-derived extracellular vehicles." (PMID 36172164, 2022). "Next, we used Tumor Immune Estimation Resource (TIMER) and CIBERSORT to analyze the relationship between MUC1 expression and tumor immune cell infiltration." (PMID 35879749, 2022). "During low oxygen (hypoxia) periods, Mucin 1 (MUC1) increases HIF-1α to stimulate tumor development and angiogenesis." (PMID 35892934, 2022). "The expression of MUC1 in the tumor and lymphatic metastasis positive samples was significantly increased." (PMID 35879749, 2022). "Siglec-9 binds to MUC1 mucin on the surfaces of human colon cancer, pancreatic cancer, and breast cancer cells, secretes tumor-related factors such as plasminogen activator inhibitor-1, and promotes tumor invasion, metastasis, and neovascularization." (PMID 35418152, 2022).